METTL3 (methyltransferase 3, N6-adenosine-methyltransferase complex catalytic subunit)
Diseases named in the same sentence as METTL3 in open-access papers (continued):
Sharing a sentence is not in itself a finding about the gene and the disease.
cancer (continued). "In numerous cancers, there is a consistent observation of dysregulated expression of key enzymes involved in m6A modification, including "writers" (such as METTL3, METTL14, WTAP), "erasers" (like FTO, ALKBH5), and "readers" (including YTHDF1, YTHDF2, YTHDF3)." (PMID 38270643, 2024). "KEGG pathway analysis of the differentially methylated genes revealed the enrichment of cancer pathway, further confirming the correlation between METTL3-mediated m6A and the occurrence and progression of GC." (PMID 38879589, 2024). "Mostly, METTL3 stimulates the occurrence and progression of diverse cancers as an oncogene, through depositing m6A modification on key transcripts." (PMID 39054967, 2024). "More importantly, CDC25A expression was positively correlated with IGF2BP3 and METTL3 expression in most cancer types in TCGA datasets." (PMID 39247830, 2024). "Previous studies have shown that METTL3 is the only catalytic subunit of the m6A methyltransferase complex that plays critical roles in various cancers." (PMID 38895621, 2024). "Among the m6A regulators in the regulatory network, we found that CAPRIN1, a novel METTL3 co-factor, was positively correlated with cancer-specific m6A." (PMID 38970366, 2024). "The present findings highlight the pivotal role enacted by METTL3‐mediated m6A modification in miRNA biogenesis, indicating its potential usefulness as a promising therapeutic target for cancer." (PMID 38380598, 2024). "Currently, METTL3-catalyzed m6A RNA methylation is widely recognized as a key epigenetic regulatory process for tumorigenic characteristics in various cancer cell lines, including BCa." (PMID 39295872, 2024). "HE and TUNEL staining showed that overexpression of METTL3 slowed down the apoptosis of cancer cells and hindered the therapeutic effect of endostar in combination with cisplatin." (PMID 38331776, 2024). "In hepatocellular carcinoma, HBXIP drives the metabolic reprogramming and malignant biological behavior of cancer cells by positively regulating the METTL3-mediated m6A modification of HIF-1α." (PMID 39759516, 2024). "This further emphasizes the widespread impact of METTL3 and m6A methylation in cancer development and precision therapy." (PMID 38605400, 2024). "Prior studies have demonstrated that METTL3 is overexpressed in various cancers and contributes to cancer progression and metastasis." (PMID 38429907, 2024). "METTL3 is the key writer of m6A methylation on mRNA, which in turn lead to increased translation of mRNAs in cancer cells." (PMID 39313128, 2024). "For instance, SAH and the broad-spectrum 2-OG oxygenase inhibitor IOX1 inhibit cancer development by targeting METTL3-METTL14 and ALKBH5, respectively." (PMID 39098905, 2024). "Inhibition of METTL3 leads to an increase in dsRNA formation, which in turn enhances interferon signaling and augments the capacity of T cells to eliminate cancer cells." (PMID 39372415, 2024). "As the most studied m6A methyltransferase, METTL3 has been reported to play roles in a variety of diseases, especially in cancer." (PMID 40453361, 2024). "For instance, using animal models of cancer, AS, and ischemic diseases can provide valuable insights into the in vivo effects of METTL3 inhibitors or enhancers." (PMID 39834386, 2024). "In cancer contexts, METTL3 has a critical function in modulating the target genes’ stability through an m6A-dependent mechanism." (PMID 38390305, 2024). "Taken together, METTL3 plays a crucial role in regulating stromal cells and their interaction with cancer cells." (PMID 38322265, 2024). "In most cases, METTL3 was reported as an oncogene to promote the initiation and development of cancers, including hematopoietic malignancies and solid tumors, through depositing m6A modification on critical transcripts." (PMID 38966069, 2024).
cancer (continued). "METTL3 is usually considered to represent a diagnosed malignant phenotype with a poor prognosis, but the finding that METTL3 can act as a prognostic factor in RCC suggests that METTL3 has complexity in serving as a cancer biomarker." (PMID 39289775, 2024). "In the present study, we investigated the cancer-promoting effect of METTL3 silencing in BrafV600E knock-in mice." (PMID 38993572, 2024). "High levels of METTL3/METTL14 drive the growth of many types of adult cancer, and METTL3/METTL14 inhibitors are emerging as new anticancer agents." (PMID 38691450, 2024). "The biological functions of METTL3 upregulation in PCa play an important role in cancer progression." (PMID 38166703, 2024). "Previous literature has reported that METTL3 is essentially involved in glucose metabolism in various cancers, but the mechanism and function of SRPK1 in glucose metabolism in LUAD remains largely undetermined." (PMID 39095708, 2024). "For instance, TBP binding to the METTL3 promoter has been shown to increase m6A methylation, impacting cancer cell metabolism and proliferation." (PMID 39434688, 2024). "Much research has indicated that METTL3 increases targeted mRNA stability in an IGF2BP2-dependent manner in cancers." (PMID 39095708, 2024). "METTL3 has been shown to translocate to the cytoplasm of cancer cells, where it orchestrates the translation of specific oncogenic transcripts." (PMID 38444581, 2024). "While there are currently no METTL1-specific inhibitors available, recent breakthroughs in the field of epitranscriptomics and cancer have led to the successful development of inhibitors targeting METTL3, an RNA 6-methyladenosine transferase." (PMID 37660182, 2023). "Previous studies have demonstrated that METTL3 participated in alterations of multiple biological functions in various cancer types by an m6A-independent or dependent manner." (PMID 37344779, 2023). "METTL3 expression was upregulated in PCa cell lines, where it knockdown-induced apoptosis in cancer cells." (PMID 38117350, 2023). "It is generally acknowledged that METTL3 exhibits oncogenic functions in most cancer types, such as acute myeloid leukemia, breast cancer, and lung cancer." (PMID 37915103, 2023). "Recently, inhibitors of the epigenetic regulator METTL3 have emerged as potential cancer therapies and are currently under evaluation in clinical trials." (PMID 37742030, 2023). "METTL3 promotes the growth, survival and invasion of lung cancer cells, and its deletion strongly inhibits cancer cell growth, increases apoptosis, and significantly reduces the invasive ability of cancer cells." (PMID 38053093, 2023). "METTL3 is overexpressed in CC and silencing of METTL3 can reduce cancer cell viability, promote apoptosis and increase cisplatin sensitivity." (PMID 37474926, 2023). "Using SPLINTR lineage tracing methodology and single-cell RNAseq of resistant clones, they discovered that anti-PD1 therapy and inhibitors of METTL3 target distinct populations of cancer cells." (PMID 38072988, 2023). "Obvious inhibitory effects on cell proliferation and colony formation were observed in cancer cells with decreased METTL3 compared with the control group." (PMID 38001065, 2023). "Knockdown of METTL3 in hepatocellular carcinoma substantially abolished cancer cell tumorigenicity and lung metastasis through augmenting SOCS2 expression relied on the YTHDF2-dependent pathway." (PMID 38001065, 2023). "Compared with wild-type group, the NF-κB mutation significantly diminished STAT3 promoter activity, and this inhibitory effect was further extended in METTL3 knockout cancer cells." (PMID 38001065, 2023). "Our experimental data first clearly and systematically indicated that METTL3 has a significant cancer-promoting effect at least in the CRPC stage." (PMID 37095108, 2023).
cancer (continued). "After METTL3 silencing, the m6A level was significantly decreased in cancer cells compared with a control group, which is in accordance with others’ previous reports." (PMID 38001065, 2023). "As research continues, it is likely that more insights will be gained into the complex and integrative role that Mettl3 plays in cancer." (PMID 37007040, 2023). "To summarize, METTL3 modified DDX23 mRNA in an m6A modification manner thus promoting cancer cell proliferation, mobility, and chemoresistance through PI3K/Akt signaling." (PMID 36977668, 2023). "Our study illustrates some findings that are consistent with those in other cancers (e.g., the association between METTL3 and MYC signaling), but we did find many PCa-specific findings that differ from other cancer types." (PMID 37675218, 2023). "Because METTL3 or FTO plays an important oncogenic role in many cancers, considerable efforts have gone into developing small-molecule inhibitors that specifically target METTL3 or FTO for cancer treatment." (PMID 39872957, 2023). "Gene amplification was also suggested as a potential mechanism for METTL3 overexpression in certain cancers." (PMID 38012755, 2023). "METTL3 plays a dual role as either an oncogene or a tumor suppressor gene in different types of cancers, with upregulated or downregulated expression." (PMID 36810281, 2023). "METTL3, an m6A “writer”, can independently or collaboratively regulate aspects of cancer, such as growth, invasion, metastasis, and drug resistance." (PMID 38112021, 2023). "Collectively, the development of these METTL3 inhibitors will greatly advance the functional study and therapeutic targeting of mRNA m6A methylation in cancer and other diseases." (PMID 37620312, 2023). "This suggests that m6A via Mettl3 has a dynamic role in the progression of the model and leads to unique changes in phenotype based on the stage of the cancer." (PMID 38023205, 2023). "As the most common catalyst of m6A modification, METTL3 has been shown to promote the progression of various cancers, such as breast, lung and gastric cancers." (PMID 37604948, 2023). "Recent studies have indicated that METTL3-mediated disorders of m6A modification are closely related to the occurrence and development of cancers." (PMID 37231451, 2023). "The role of m6A in cancer is bidirectional; for instance, in colorectal cancer, SOX2 exerts a pro-cancer effect via METTL3-catalyzed methylation." (PMID 36830673, 2023). "Overexpression of Mettl3 promotes cancer progression through various pathways, such as affecting glucose metabolism, cell cycle PD-L1, immune infiltration, and enhancing the stability of oncogenic mRNA to promote the proliferation and migration of CC cells." (PMID 37007040, 2023). "Recently, PD-L1 expression has also been found to be regulated by some other m6A regulators in other types of cancer, such as mediated by METTL3 in OSCC, by FTO in colon cancer cells, and by YTHDF1 and YTHDF2 in NSCLC." (PMID 36960074, 2023). "We summarize the mechanisms of m6A involvement in cancer and list potential cancer therapy inhibitors that target m6A regulators such as “writer” METTL3 and “eraser” FTO." (PMID 39872957, 2023). "METTL3 was the first identified m6A writer and the only catalytic subunit, and its upregulation in PCa translates into playing important roles in cancer progression." (PMID 38117350, 2023). "Given the role of m6A modifications in the regulation of gene expression, the catalytic subunit m6A-METTL complex (MAC)-METTL3/14 has emerged as a key player in various biological processes, including cancer development and progression." (PMID 38187373, 2023). "In short, Mettl3 exerts a significant and multifaceted biological impact on diverse cancer types and all stages of tumorigenesis." (PMID 37007040, 2023). "SNHG17 has high expression in many cancer tissues and can be induced by many factors including m6A methyltransferase METTL3." (PMID 36635762, 2023).
cancer (continued). "The inhibition of METTL3 resulted in decreased m6A methylation of KIF26B mRNA, a gene associated with cell-cell adhesion and important for cancer cell invasion." (PMID 38023192, 2023). "Depending on the presence of m6A modifications, the translation of the target gene mRNA can be promoted by METTL3, thus leading to malignant cancer development, including AML, ovarian cancer, and colorectal cancer (CRC)." (PMID 38102645, 2023). "Although mechanisms of METTL3 in many cancers have been well documented, the role of METTL3 in PCa-related AS switch has been poorly explored." (PMID 37675218, 2023). "METTL3 was reported to have a critical m6A-dependent role in facilitating cancer progression and metastasis by an m6A dependent manner." (PMID 37156816, 2023). "In recent years, an increasing number of researchers have demonstrated that METTL3 promotes cancer cell proliferation, apoptosis and metastasis by accelerating miRNA maturation in an m6A-dependent manner." (PMID 36348020, 2023). "METTL3, the main m6A methyltransferase, is involved in the progression of several types of cancers, including acute myeloid leukemia, hepatocellular carcinoma, and lung cancer." (PMID 38023192, 2023). "At present, the small molecule candidate drug STM2457 targeting METTL3 is expected to enter the clinical trial stage, which has a significant possibility to become the first RNA epigenetic drug for cancer therapy." (PMID 36260366, 2023). "According to high throughput cancer cell line CRISPR screenings, METTL16 appears to play a more important role in cancer cell survival and proliferation than METTL3." (PMID 37817227, 2023). "By conducting this comprehensive study, we provided a deeper understanding of the role of METTL3 in cancer and its potential as a therapeutic target." (PMID 38012755, 2023). "The function of METTL3 in DSB repair has provided insights into the role of METTL3 in the radioresistance of cancer cells." (PMID 38201270, 2023). "Tumor suppressor functions of METTL3-METTL14 complex have also been reported the in several cancer models." (PMID 37612540, 2023). "In acutemyeloid leukemia (AML), METTL3 has been identified asan essential gene for cancer cell growth in two genetic screens." (PMID 36692498, 2023). "Although studies on the oncogenic role of METTL3 in human cancers are still limited, potential clinical applications for METTL3 have recently emerged in the form of substrate competitive inhibitors of METTL3." (PMID 37344779, 2023). "The results showed that METTL3 knockdown resulted in alterations in many cancers and cell proliferation-related genes, such as the FOXO signaling pathway, G2M Checkpoint, E2F Targets, and DNA repair hallmark." (PMID 37675218, 2023). "METTL3 is an m6A methyltransferase that has been studied extensively owing to its roles in various cancers." (PMID 37965577, 2023). "Several studies have revealed that METTL3, a core component of m6A methyltransferase, is significantly upregulated in BCa and contributes to cancer progression." (PMID 38117350, 2023). "By reducing METTL3 expression, cancer cells can be less capable of migrating, invading, and undergoing epithelial-mesenchymal transitions." (PMID 37833349, 2023). "METTL3 is the most studied and important m6A methyltransferase, “Writer”, which plays a key role in a variety of cancers (including GC)." (PMID 37443100, 2023). "Consistent with previous reports, We confirmed the high expression of METTL3 in 18 pan-cancer types including STAD from the TCGA database." (PMID 37344779, 2023). "The forced silence of METTL3 and DDX23 led to suppressed cancer phenotypes and in vivo malignancy, showing the potential of METTL3/DDX23 axis as therapeutic targets for PDAC." (PMID 36977668, 2023). "Compared with m6A erasers, m6A writers, especially METTL3, plays more critical roles in the regulation of cancer metabolism." (PMID 36260366, 2023).
cancer (continued). "dCas13b-METTL3, a m6A editing tool based on CRISPR system, proves that METTL3-catalyzed HMBOX1 methylation is involved in regulating telomerase recruitment, resulting in telomere loss in cancer cells, and m6A is involved in carcinogenesis." (PMID 37519297, 2023). "METTL3 has been widely studied and reported to play diverse roles in the onset and proliferation of tumors, and its biofunctional spectrum in human cancers has gradually been completed in recent years." (PMID 37095108, 2023). "Recently, METTL3 was reported to play an oncogenic role in various cancers, providing an opportunity for the development of effective targeted therapeutics." (PMID 38001065, 2023). "Differential metabolite KEGG analysis further demonstrated that the expression of METTL3 is involved in central carbon metabolism in cancer, especially in glycolysis and gluconeogenesis." (PMID 36609396, 2023). "Elevated or declined expression of the essential m6A-catalyst METTL3 was reported in diverse cancer types." (PMID 37370759, 2023). "There is mounting evidence indicating that methyltransferase-like 3 (METTL3) is a critical factor in multiple human cancers, primarily due to its activity as an m6A RNA methyltransferase." (PMID 38260844, 2023). "Here, we show that the cleaved form METTL3a plays a key role in m6A methylation activity, thus providing another potential anti-cancer therapeutic approach through blockade of METTL3 cleavage." (PMID 37589705, 2023). "At present, a number of studies have demonstrated that m6A methyltransferase like 3 (METTL3) is dysregulated in a variety of human malignant tumors and has carcinogenicity." (PMID 37936074, 2023). "Although METTL3 has been extensively studied for over a decade, our knowledge about its role in cancer is still limited." (PMID 36725888, 2023). "As an important N6-methyladenosine (m6A) regulator, abnormal expression of methyltransferase-like protein 3 (METTL3) has been reported in certain human cancers." (PMID 35794583, 2022). "METTL3 regulates cerebellar development, spermatogonial differentiation, and various biological processes in different cancers." (PMID 36614956, 2022). "Although the role of METTL3 in modulating cancer cell survival and apoptosis has been well described, the role of METTL3 in MI is yet to be explored." (PMID 35452193, 2022). "METTL3 has been proven to be involved in drug resistance in many cancers, but opposite roles have also been found in various cancer treatment models." (PMID 36266324, 2022). "Meanwhile, METTL3 plays a role in BCa progression by promoting the cancer cell growth and invasion by regulating a network that involves the AF4/FMR2 family member 4 (AFF4), nuclear factor-kappa B (NF-κB), and Myc." (PMID 35148766, 2022). "Accumulating evidences in recent years demonstrate that METTL3, in most cases, plays as an oncogene in cancer." (PMID 35541906, 2022). "Accordingly, miR-1269b can affect the progression of cancer by targeting downstream genes (METTL3, CDC40, SVEP1, and PTEN)." (PMID 35252180, 2022). "This study was conducted to analyze the expression profiles of METTL3 and its prognostic value in pan-cancer." (PMID 36614956, 2022). "Accumulating evidence in recent years revealed that m6A modification by METTL3 enzyme participates in many pathological processes including cancer." (PMID 36183833, 2022). "Collectively, these data indicate a potential correlation among the invasiveness of cancer cells, the nuclear accumulation of METTL3, and METTL3 acetylation status." (PMID 36289222, 2022). "Glycolysis is a major glucose metabolic pathway upregulated in cancer cells, and METTL3 has been shown to upregulate expression of multiple glycolytic enzymes." (PMID 36289851, 2022). "METTL3 promotes cancer progression, such as in hepatocellular carcinoma, pancreatic cancer, lung cancer, and acute myeloid leukemia." (PMID 35436987, 2022).